MT1F (metallothionein 1F)
Description:
Metallothioneins have a high content of cysteine residues that bind various heavy metals; these proteins are transcriptionally regulated by both heavy metals and glucocorticoids.
Synonyms: MT1
Tractability: PROTAC: ubiquitination databases record sites on it.
Gene: Protein-coding gene on chromosome 16 (56,657,640 to 56,660,698, forward strand). Ensembl gene ENSG00000198417.
Pathways (Reactome):
Cellular responses to stimuli: Metallothioneins bind metals
Gene Ontology:
Molecular function: protein binding; metal ion binding; zinc ion binding
Biological process: cellular response to cadmium ion; cellular response to copper ion; cellular response to zinc ion; detoxification of copper ion; intracellular zinc ion homeostasis; negative regulation of growth
Cellular component: cytoplasm; nucleus
Genetic constraint (gnomAD): Loss-of-function variants: 11 observed, 9.4 expected, observed/expected ratio (o/e) 1.17, 90% interval 0.73 to 1.8. That is too few expected variants to judge how well the gene tolerates losing a copy. Missense variants: 82 observed, 82.02 expected, observed/expected ratio (o/e) 1, 90% interval 0.83 to 1.2. Synonymous variants: 28 observed, 30.44 expected, observed/expected ratio (o/e) 0.92, 90% interval 0.68 to 1.26.
Homologues: Orthologues: chimpanzee MT1F (98% identical), macaque MT1F (85% identical), zebrafish mt2 (66% identical). Paralogues in human: MT1G (93% identical), MT2A (92% identical), MT1A (87% identical), MT1H (87% identical), MT1B (85% identical), MT1HL1 (85% identical), MT1X (84% identical), MT1M (82% identical), MT3 (74% identical), MT4 (59% identical), MT1E (57% identical).
Diseases named in the same sentence as MT1F in open-access papers:
MT1F is named in the same sentence as 33 diseases in open-access papers, as found by Europe PMC text mining. Sharing a sentence is not in itself a finding about the gene and the disease. The quoted sentences say what the papers report.
colon carcinoma (9 papers, 2013 to 2023). "In human colon carcinoma downregulation of a specific isoform of MT (MT1F) resulted from loss of heterozygosity." (PMID 36759896, 2023). "Loss of heterozygosity (LOH) causes the downregulation of MT1F in colon cancer tissues, suggesting a tumor suppressor role for MT1F in colon cancer." (PMID 28241806, 2017). "The downregulation of MT1F in colon cancer is mainly caused by loss of heterozygosity (LOH)." (PMID 28241806, 2017). "MT1F acts as a tumour suppressor in colon cancer, gastric cancer, and liver cancer and as an oncogene in lung cancer and breast cancer." (PMID 36059811, 2022). "MT1F expression is typically down-regulated in a majority of human colon tumor tissues and its enforced expression can result in increased apoptosis and inhibition of cell migration, invasion and in vivo tumorigenicity." (PMID 25248511, 2014). "Intriguingly, in vitro experiments have confirmed that MT1F transfection into colon cancer cells could decrease cell proliferation and colony formation and increase cell apoptosis rates to inhibit cell growth." (PMID 30139373, 2018). "Furthermore, exogenous MT1F expression increased colon cancer cell line (RKO) apoptosis and inhibited RKO cell migration, invasion and adhesion, as well as in vivo tumorigenicity." (PMID 23502468, 2013). "Previous studies have indicated that MT1E, MT1F and MT1M are antitumor genes in malignant melanoma, colon carcinoma cells, and hepatocellular carcinoma HepB3, respectively." (PMID 36009228, 2022).
breast carcinoma (8 papers, 2009 to 2024). "Gene MT1F (UniGene Hs.438737) is found to be associated with six types of cancers (all except breast cancer)." (PMID 19919702, 2009). "In further investigations, four breast cancer cell lines were screened for mRNA expression of MT1F, MT1E, SLC30A1, and S100P after treatment with BA or CAI3 and showed an upregulation of MT1F, MT1E, SLC30A1, and S100P in four breast cancer cell lines." (PMID 39594441, 2024). "Previous studies have linked the down-regulation of MT1F, MT1G, and MT1H to hepatocellular carcinoma, and the down-regulation HOXA to breast cancer with the whole cluster silenced." (PMID 32841292, 2020). "Overall, all genes showed lower expression in four breast cancer cell lines than in the HMEC cell line, except MT1F and MT1X, where MT1F has lower in HMEC than in MCF7 and MDA-MB231 cells, and MT1X has a similar level in MDA-MB231 cells." (PMID 25763113, 2015). "Cell proliferation and invasion assays suggested MT1F and MT1M may play an anti-oncogenic role in breast cancer." (PMID 25763113, 2015). "Cell proliferation and invasion assays suggested MT1F and MT1M may have anti-oncogenic roles in breast cancer." (PMID 25763113, 2015).
hepatocellular carcinoma (4 papers, 2020 to 2024). A malignant tumor that arises from hepatocytes. "Genes like MT1E and MT1F can be used as biomarkers to predict the recurrence of hepatocellular carcinoma." (PMID 39061894, 2024).
lung carcinoma (4 papers, 2014 to 2023). "The authors found MT-1A C/A, MT-1B G/A and MT-1F C/T variants to significantly increase the risk of lung cancer." (PMID 36981043, 2023). "Therefore, the general increase in expression of MT1F during aging may function as a protective mechanism to prevent development of cancer, whereas smoking-dependent down-regulation in the small airway epithelium may contribute to the increased risk of developing lung cancer in smokers." (PMID 25248511, 2014). "However, additional in vitro studies need to be performed to demonstrate a role of MT1F in development of lung cancer in addition to following subjects over time to confirm the correlation between MT1F expression and development of lung cancer and/or COPD." (PMID 25248511, 2014). "Hence, the upregulation of MT1B, MT1F, MT1G, and MT1H in HPAEpiCs after exposure to PHMG may be involved in the development of lung cancer." (PMID 34564354, 2021).
colorectal cancer (2 papers, 2016 to 2023). A primary or metastatic malignant neoplasm that affects the colon or rectum. "In vitro and in vivo experiments have confirmed that MT1F in colorectal cancer cells could decrease cell proliferation and colony formation, increase the rate of apoptosis to inhibit cell growth, and reduce xenograft tumor growth in MT1F-expressing mice." (PMID 38068944, 2023).
non-small cell lung carcinoma (2 papers, 2018 to 2024). A group of at least three distinct histological types of lung cancer, including non-small cell squamous cell carcinoma, adenocarcinoma, and large cell carcinoma. "Studies have shown that MT1F is associated with poor clinical outcomes in non-small cell lung cancer." (PMID 38747739, 2024).
Parkinson disease (2 papers, 2013 to 2023). A progressive degenerative disorder of the central nervous system characterized by loss of dopamine producing neurons in the substantia nigra and the presence of Lewy bodies in the substantia nigra and locus coeruleus. "Metallothioneins are up-regulated in neurodegenerative disorders and in metabolic stress; both MT1H and MT1F were up-regulated in substantia nigra and frontal cortex of Parkinson’s disease patients." (PMID 37629120, 2023).
psychosis (2 papers, 2008 to 2023). "Using a quantitative PCR, we validated a set of genes such as up-regulated metallothioneins (MT1E, MT1F, MT1H, MT1K, MT1X, MT2A and MT3) and down-regulated neuropeptides (SST, TAC1 and NPY) in the dorsolateral prefrontal cortex of psychosis patients." (PMID 18992145, 2008). "In the current cross-study analysis, we identified a set of metallothionein genes including MT1X, MT1K, MT1E, MT1H, MT1F, MT2A and MT3 that are significantly up-regulated in psychosis." (PMID 18992145, 2008). "In a study conducted on postmortem subjects with and without psychosis, up-regulation in MT1E, MT1F, MT1H, MT1K, MT1X, MT2A, and MT3 genes was observed in the dorsolateral prefrontal cortex." (PMID 36831126, 2023).
Arthritis (1 paper, 2024). Inflammation of a joint. "Through MR analysis, we have deduced that MT-1F plays a protective role in the occurrence of arthritis." (PMID 38720162, 2024).
Down syndrome (1 paper, 2022). "The present validation study confirmed that the genes for the MT1F, MT1X, MT1M, MT1E, and MT2A isoforms exhibit a statistically significant alteration of expression in Down’s syndrome patients with active periodontal disease and implant failure." (PMID 35741790, 2022).
schizophrenia (1 paper, 2017). A major psychotic disorder characterized by abnormalities in the perception or expression of reality. "The paralogous genes of GBP1, MT2A and APOL1, including GBP2, MT1G, MT1E, MT1F, MT1L and APOLD1, were also upregulated in the schizophrenia cases." (PMID 28809853, 2017).
viral infection (1 paper, 2020). "In relevance to viral infection, MT1F, MT1G, and MT1H proteins exerted some amount of antiviral activity against Hepatitis C viruses (HCV), while HOXA10 was shown to suppress Hepatitis B viruses (HBV) replication." (PMID 32841292, 2020).
tumor (23 papers, 2007 to 2025). "The MT1M gene was selected because it is highly methylated in ERα + cells and has been implicated as a tumor suppressor in earlier studies, while the selection of MT1F is because it is most highly expressed in MCF7 cells compared to other cell lines." (PMID 25763113, 2015). "As tumor suppressor, metallothionein 1F (MT1F) has been shown to be down regulated in several tumors as part of cancer initiation and/or progression." (PMID 28938650, 2017). "The BCL2L2 of the Bcl-2 family is an important anti-apoptotic gene, and suppression of its expression sensitizes cells to anticancer drugs, whereas MT1F exerts its tumor-suppressive ability by inducing apoptosis." (PMID 24019915, 2013). "Among 15 genes in the signature, except four genes, RAB27A, ADGRB1, MT1F, and TPT1, the remaining were differentially expressed between tumor and normal tissues." (PMID 33329725, 2020). "Apart from MT1B, MT1F, and MT4, other MT isoforms in tumor tissue were both downregulated significantly in Oncomine and GEPIA databases." (PMID 31380415, 2019). "Therefore, the four MT1s (MT1G, MT1E, MT1F and MT1X) are down regulated in tumor samples, at the same time, they are also down regulated in tumor samples with MT1 deletion, indicating that MT1 deletion may affect the expression of its genes in HCC." (PMID 34257549, 2021).
cancer (11 papers, 2007 to 2025). A tumor composed of atypical neoplastic, often pleomorphic cells that invade other tissues. "For example, gene MT1F is identified to be associated with six types of cancers." (PMID 19919702, 2009). "The mechanisms underlying MT1F induced alteration in cancer is largely unknown." (PMID 29228617, 2017). "While down-regulated genes were associated with GO categories such as cellular response to zinc ion where members of metallothionein family (MT1M, MT1H, MT1X, MT1G, and MT1F) play important roles in carcinogenesis of various cancer types." (PMID 32849813, 2020). "Strikingly, members of the metallothionein family, including MT1M, MT1H, MT1G, MT1F, MT1E, MT1X, and MT1A, were significantly downregulated in cancer cells." (PMID 35967424, 2022). "A majority of cuproptosis-related genes like CP, MT1E, MT1F, MT1X, VEGFA, and PDK1 were expressed significantly higher on cancer cells, indicating that cuproptosis might occur mainly on cancer cells." (PMID 36211378, 2022).
MT1F also shares sentences with these, for which no sentence is quoted: gastric cancer (3 papers); infection (2); malignant melanoma (2); Alzheimer disease (1); amyloidosis (1); anemia (1); cholestasis (1); clear cell renal cell carcinoma (1); colorectal tumor (1); glioma (1); leukemia (1); liver cancer (1); malnutrition (1); metabolic disease (1); osteoarthritis (1); osteosarcoma (1); periodontal disease (1); Sepsis (1); small cell lung carcinoma (1).